GCFC2 (GC-rich sequence DNA-binding factor 2)
Description:
Involved in pre-mRNA splicing through regulating spliceosome C complex formation. May play a role during late-stage splicing events and turnover of excised introns.
Synonyms: C2orf3; GCF; TCF9; DNABF
Tractability: PROTAC: ubiquitination databases record sites on it; its protein half-life has been measured.
Gene: Protein-coding gene on chromosome 2 (75,652,000 to 75,711,184, reverse strand). Ensembl gene ENSG00000005436.
Subcellular location: Nucleus, nucleoplasm; Nucleus, nucleolus
Subcellular location (Human Protein Atlas): Nucleoplasm
Pathways (Reactome):
Metabolism of RNA: mRNA Splicing - Major Pathway
Gene Ontology:
Molecular function: protein binding; DNA binding
Biological process: spliceosomal complex assembly; mRNA splicing, via spliceosome
Cellular component: nucleolus; nucleoplasm; nucleus; U2-type post-mRNA release spliceosomal complex
Genetic constraint (gnomAD): Loss-of-function variants: 10 observed, 6.18 expected, observed/expected ratio (o/e) 1.62, 90% interval 0.94 to 1.95. That is too few expected variants to judge how well the gene tolerates losing a copy. Missense variants: 257 observed, 158.44 expected, observed/expected ratio (o/e) 1.62, 90% interval 1.46 to 1.8. Synonymous variants: 97 observed, 65.08 expected, observed/expected ratio (o/e) 1.49, 90% interval 1.26 to 1.76.
Homologues: Orthologues: chimpanzee GCFC2 (98% identical), macaque GCFC2 (95% identical), dog GCFC2 (80% identical), pig GCFC2 (79% identical), guinea pig GCFC2 (73% identical), mouse Gcfc2 (69% identical), rat Gcfc2 (69% identical), rabbit GCFC2 (55% identical), tropical clawed frog gcfc2 (43% identical), zebrafish gcfc2 (32% identical), Drosophila melanogaster CG1965 (28% identical), Caenorhabditis elegans mog-7 (21% identical). Paralogues in human: PAXBP1 (33% identical).
Diseases named in the same sentence as GCFC2 in open-access papers:
GCFC2 is named in the same sentence as 6 diseases in open-access papers, as found by Europe PMC text mining. Sharing a sentence is not in itself a finding about the gene and the disease.
GCFC2 shares sentences with these, for which no sentence is quoted: dyslexia (4 papers); anemia (1); brain cancer (1); epilepsy (1); neurological disease (1); schizophrenia (1).